CRP (C-reactive protein)
Diseases named in the same sentence as CRP in open-access papers (continued):
Sharing a sentence is not in itself a finding about the gene and the disease.
pulmonary fibrosis (55 papers, 2014 to 2025). Chronic progressive interstitial lung disorder characterized by the replacement of the lung tissue by connective tissue, leading to progressive dyspnea, respiratory failure, or right heart failure. "CRP (rho:0.449, p=0.009), LTα (rho:0.487, p=0.004), and IL-6 (rho: 0.400, p=0.021), all of which are associated with lung fibrosis were found to correlate with Gal9 levels." (PMID 40977722, 2025). "Another recent study showed that epidermic growth factor receptor (EGFR) positivity and pulmonary fibrosis are associated with increased D-dimer levels, CRP levels, and prolonged ICU stay." (PMID 37893011, 2023). "In terms of inflammatory markers, patients with pulmonary fibrosis were associated with a significantly higher mean CRP value than patients in the first group (p = 0.048)." (PMID 38256314, 2023). "Several studies tried to identify predictive factors, such as patients’ age, presence of digital ulcer, lung fibrosis, and CRP elevation, that are associated with a fast disease progression and lead to organ failure." (PMID 33441156, 2021). "Active DU, CRP elevation, lung fibrosis and muscle weakness were also associated with a significantly shorter time to disease progression." (PMID 31227488, 2019). "After adjustment for age, gender, smoking, drinking, body mass index, and pulmonary fibrosis/infection, multiple linear regression models demonstrated that CRP is associated with HDL-C among PM patients (P = 0.028)." (PMID 24587064, 2014). "After adjustment for age, gender, smoking, drinking, body mass index, and pulmonary fibrosis/infection, linear regression model demonstrated that CRP is associated with HDL-C among PM patients (P = 0.028)." (PMID 24587064, 2014). "A higher intensity of the inflammatory process, associated with higher levels of CRP and IL-6 in patients, might lead to lung fibrosis during recovery." (PMID 36010377, 2022). "The additional analysis of four risk factors on their own showed that each (active DU, raised CRP, presence of lung fibrosis and muscle weakness) was associated with a significantly increased incidence of outcome events during follow-up as well as in combination (each p<0.001 by log-rank test)." (PMID 31227488, 2019). "Thus, high levels of circulating CRP may increase the risk of IPF by affecting pathways associated with pulmonary fibrosis." (PMID 36624433, 2023). "Through activation of the NF-κB pathway, CRP also contributes to extracellular matrix accumulation and the development of pulmonary fibrosis." (PMID 41225615, 2025). "Similar to the long COVID patients with pulmonary symptoms, elevated levels of IL-6, CRP, and TGF-β were identified in patients at increased risk of developing pulmonary fibrosis after SARS-CoV-2 infection." (PMID 36744129, 2023). "In vivo, the LF-Zn-NPs displayed a protective and therapeutic activity against induced pulmonary fibrosis in Bleomycin-treated male albino rats owing to its anti-inflammatory, antioxidant, and significant reduction in CRP, LDH, ferritin, and D-dimer levels." (PMID 37741872, 2023). "Several observational studies have found that idiopathic pulmonary fibrosis (IPF) is often accompanied by elevated circulating C-reactive protein (CRP) levels." (PMID 36624433, 2023). "CRP-mediated activation of complement and macrophages is suspected to be a driver of human pulmonary fibrosis and subsequent organ failure." (PMID 35874670, 2022). "It was found that the severity of EGFR involvement and pulmonary fibrosis in patients who died from COVID-19 pneumonia correlated with CRP levels." (PMID 36353282, 2022). "Specifically, we tested the most clinically feasible combinations of increased CRP and presence of lung fibrosis or DU." (PMID 31227488, 2019). "There was substantial evidence for a strong association between disease progression and age, active digital ulcer (DU), lung fibrosis, muscle weakness and elevated C-reactive protein (CRP) level." (PMID 31227488, 2019).
pulmonary fibrosis (continued). "Although self-reported muscle weakness is difficult to use in clinical trials, an increased CRP and the presence of lung fibrosis and DUs are feasible inclusion criteria for further clinical trials." (PMID 31227488, 2019). "If patients had lung fibrosis, muscle weakness, DU and CRP elevation, the probability for an event was 74.5% at 60 years and 78.8% at 70 years." (PMID 31227488, 2019). "In the largest biomarker study in idiopathic pulmonary fibrosis to date, remodeling of the interstitial matrix and proteolytic degradation of CRP was also shown to be related to disease progression and mortality." (PMID 27716343, 2016). "In the present study, we found a close association between CRP and HDL-C after controlling for age, gender, smoking, drinking, body mass index and pulmonary fibrosis/infection." (PMID 24587064, 2014). "Elevated CRP is a well-established marker of systemic inflammation and is involved in the pathogenesis of pulmonary fibrosis by promoting alveolar epithelial injury and fibroblast activation through interleukin-6 (IL-6) and transforming growth factor-beta (TGF-β) signaling pathways." (PMID 41277954, 2025). "IL-6 and IL-1β stimulate the production of C-reactive protein (CRP), which mediates systemic inflammatory responses, while TNF-α stimulates fibroblast proliferation and collagen fiber synthesis, which subsequently cause pulmonary fibrosis." (PMID 35062368, 2022). "Genetically determined CRP displayed negative associations with degenerative macular diseases, metatarsalgia, interstitial lung disease, idiopathic pulmonary fibrosis, and radiation-related disorders of the skin and subcutaneous tissue." (PMID 34386016, 2021). "Moreover, reduced circulating iNKT cell numbers are found to be associated with signs of pulmonary fibrosis on CT scans and other clinical indicators of disease severity or activity, such as reduced FVC and increased C-reactive protein (CRP)." (PMID 34868074, 2021). "As suggested by the high ORs for lung fibrosis and CRP elevation, these two factors alone increased the probability for an event during the observation time to 52.0% in patients aged 60 years and 57.9% in patients aged 70 years compared with 32.2% for the overall study population." (PMID 31227488, 2019). "Based on our logistic regression model, we showed that the probability of a 60-year-old patient with lung fibrosis, DU, muscle weakness and CRP elevation developing disease worsening within the observation period increases to 74.5% compared with 32.2% for the whole study population." (PMID 31227488, 2019). "In our study, both ESR and fibrinogen demonstrated a significant association with lung fibrosis at the 3-month and 2-year evaluations, with ESR showing higher correlation coefficients and AUC values compared to other inflammatory markers such as CRP, fibrinogen, ferritin, IL-1 and IL-6." (PMID 39767173, 2024). "However, depending on the number of predictors included, the number of selected patients decreased, for example, the optimal combination for maximum enrichment left only eight patients who had lung fibrosis, muscle weakness, CRP elevation and present DUs in our study population." (PMID 31227488, 2019). "In addition to being predictive in our model for progression of disease after 12±3 months, the presence of DU, lung fibrosis, CRP elevation and muscle weakness could also predict, alone or in combination, disease progression over a longer period of time (up to 6 years after the baseline visit)." (PMID 31227488, 2019). "Others found that low levels of vitamin D were associated with different disease activity markers in SSc (e.g., disease duration, ESR, CRP values, the presence of ACA, systolic PAH, pulmonary fibrosis, and nailfold capillaroscopic pattern)." (PMID 31823821, 2019).
pulmonary fibrosis (continued). "There was substantial evidence for a strong association between disease progression and age, active digital ulcers (DUs), C-reactive protein (CRP) elevation, lung fibrosis and muscle weakness." (PMID 31227488, 2019). "Although it is possible that IL-6 will play a role in lung fibrosis, both IL-6 and CRP are non-specific for ILD, as their levels can be elevated in almost any inflammatory condition." (PMID 37892818, 2023). "In retrospective studies from China, higher levels of serum lactic dehydrogenase and inflammatory biomarkers, including C-reactive protein (CRP), and interleukin-6 (IL-6) were found in the subgroups of patients who presented changes compatible with pulmonary fibrosis on follow-up CT scans." (PMID 37371834, 2023). "As we expected, IL-6, TNF-α, CRP, and D-dimer levels were all reduced after lenalidomide treatment, which is consistent with previous findings that lenalidomide attenuated IL-6 and TNF-α secretion in a pulmonary fibrosis model and mantle cell lymphoma." (PMID 35967862, 2022). "The aim of this study was to understand whether blood biomarkers such as pro-inflammatory markers (i.e., C reactive protein, CRP) and cytokines (i.e., IFN-I) could predict lung fibrosis-like changes in PC patients." (PMID 34944747, 2021). "The observational evidence for the effect of CRP on metatarsalgia, idiopathic pulmonary fibrosis, and disorders of the skin remains lacking." (PMID 34386016, 2021). "Age, gender, CCI score, tumor size, pretreatment CRP, SUVmax, history of other tumor, history of primary lung tumor, GOLD stage, the reason for referral to SBRT and pretreatment pulmonary fibrosis biomarker values (SP-D and KL-6) were analysed as clinical variables." (PMID 32383730, 2020). "Furthermore, PIIIN-P was positively correlated with CRP, PCT, CLR, NLR, SCC and ProGRP suggesting that the increase of inflammation may accompany and promote the progress of pulmonary fibrosis." (PMID 37860066, 2023). "Moreover, even after adjusting for IL6, VEGF, and CRP, ICAM1 + EVs remained an independent predictive factor of ILD progression, indicating that ICAM1 + EVs could be a crucial proinflammatory/profibrotic signal pathway in lung fibrosis." (PMID 40370719, 2025). "In IL-10 knockout mice, the protective effects of CRP and SAP on inflammation, nephritis, EAE, and lung fibrosis is reduced or absent, suggesting that these systemic pentraxins can act to quench ongoing inflammatory responses." (PMID 28619036, 2017).
infarction (54 papers, 2010 to 2025). A localised pathological necrosis of tissue resulting from obstruction of the blood supply usually by a thrombus, an embolus, or vascular torsion. "Studies have demonstrated that human CRP production increases significantly after AMI and peak post-infarction plasma levels of CRP are strongly associated with early and late clinical outcomes and even 30-day mortality." (PMID 40649166, 2025). "On the other hand the 12-hour measurement and delta hs-CRP were significantly associated with infarct size." (PMID 26631004, 2015). "GOT levels are independently influenced by cerebral infarct volume, but are also associated with CRP levels (β = 0.18)." (PMID 24903748, 2014). "Admission findings included elevated CRP levels (3.70 mg/dL) and a fresh infarction in the left corona radiata." (PMID 40497194, 2025). "In fact, infarction size was significantly correlated with peak C-reactive protein (ρ = 0.49; p = 0.002) in our cohort." (PMID 36142218, 2022). "The initial CRP level, however, and the post-infarction architecture of the heart determines its functionality in the later life of the infarction patient." (PMID 36362673, 2022). "In the same study, significant evidence was also found that reduction in CRP levels conferred a better outcome in terms of infarct size and cardiac output." (PMID 35407379, 2022). "For our study, the setting of acute STEMI was chosen because of substantial pre-clinical data as well as post-mortem observations on CRP's involvement in post-infarction myocardial damage." (PMID 33778017, 2021). "The CRP gradient represents the post-infarction CRP kinetic and allows valid prediction of expected CRP exposure to the patient before apheresis." (PMID 33778017, 2021). "Hepatic production of CRP is increased upon stimulation by various cytokines derived from innate immune response evoked by myocardial ischemia and infarction." (PMID 32912149, 2020). "DSY decreased the infarction size, IL-6, CRP, TNF-α, and MAD, as well as enhanced SOD activities and glutathione." (PMID 30918578, 2019). "OPG remained associated with infarct size and LVEF after adjustment for relevant covariates, except peak troponin T and CRP." (PMID 28253327, 2017). "A radiological pattern with disseminated infarctions of different size, a high D-dimer and CRP level, and an elevated prothrombin time are strong indicators of cancer-related stroke, but not specific to the pancreatic location." (PMID 27368015, 2016). "The largest of these looked at the postmyocardial infarction CRP rise and, like us, found higher levels in carriers of the rare allele of rs3093059 and also the A allele of rs3091244, which is on the same haplotype." (PMID 20877716, 2010). "Regression analyses and assessments of predictive power were adjusted for key variables, including maximum cardiac biomarker levels, sex, age, infarction type, time from symptom onset to admission, infarct-related vessel, and high-sensitivity C-reactive protein (hs-CRP)." (PMID 41464228, 2025). "As the infarct area increases and neurological deficits worsen, hs-CRP levels rise, suggesting that hs-CRP may have certain significance in the occurrence, prognosis, and treatment assessment of T2DM-AIS patients." (PMID 40313488, 2025). "In addition, up-regulation of serum miR-146b was strongly correlated with plasma CRP, infarction volume, and NIHSS scores, and also correlated with serum IL-6." (PMID 39001884, 2024). "The severity, infarct size, and prognosis of AIS patients have all been linked to CRP levels." (PMID 37777768, 2023). "Previously, studies have manifested that elevated CRP can predict LVSD and left ventricular remodeling (LVR) in patients with acute segmental elevation myocardial infarction, and suggest that LVSD patients have an increased risk of HF after infarction." (PMID 36966338, 2023).
infarction (continued). "Finally, regarding the spleen, notably elevated CRP can be seen in spleen volvulus, spleen thrombosis and infarction, as well as spleen abscess (135 mg/L case-reported for abscess; mean value of a study on spleen infarction was approx. half of this value)." (PMID 37873776, 2023). "Interestingly, preliminary evidence on adult rats have revealed that human CRP can increase cerebral infarct size after middle cerebral artery occlusion." (PMID 37873776, 2023). "In addition, CRP levels positively correlated with infarction volume compared with other laboratory tests and proinflammatory cytokines." (PMID 36079002, 2022). "The data suggested that BXT could decrease the infarction size, myeloperoxidase, interleukin-6 (IL-6), and levels of C-reactive protein (CRP) and enhance SOD activities and anti-inflammatory media such as interleukin-10 (IL-10)." (PMID 30918578, 2019). "High sensitivity C reactive protein (hs-CRP), an important inflammation biomarker, was found to be significantly increased in post-infarction subjects in relation to controls, for both smokers (0.87 ± 0.2 vs. 0.39 ± 0.05, p < 0.05) and non-smokers (0.86 ± 0.28 vs. 0.3 ± 0.05, p < 0.05)." (PMID 25257356, 2014). "Furthermore, post-infarction patients had elevated hs-CRP, MDA, CAT and GPx levels compared to controls for both smokers and non-smokers." (PMID 25257356, 2014). "In addition, CRP played a decisive role in secondary tissue damage in cardiac infarction and, vice versa, apheresis of CRP could reduce damaged infarction area questioning the black-and-white perception of CRP as a being invariably beneficial." (PMID 35402541, 2022). "There were several possibilities contributing to these contradictory conclusions: first, serum C-reactive protein (CRP), a marker of an acute inflammatory response, has been reported to rise sharply after transmural AMI, and it plateaued on day 3 after infarction." (PMID 35419440, 2022). "Based on the AUC of 0.825, FFA showed a markedly greater discriminatory ability when compared with the Hs-CRP (AUC, 0.668; 95% CI, 0.601–0.738; P < 0.001), the NIHSS score (AUC, 0.744; 95% CI, 0.667–0.811; P < 0.01), and infarct volume (AUC, 0.584; 95% CI, 0.503–0.665; P < 0.0001)." (PMID 26236218, 2015). "After adjustment for relevant clinical covariates in multivariable regression analyses (i.e. age, gender, time from symptom onset to PCI, infarct localization) OPG remained significantly associated with infarct size and LVEF, but not after adjustment for peak TnT and peak CRP." (PMID 28253327, 2017). "Thus, elevation of serum CRP levels in acute MI patients may not be an epiphenomenon of the infarction, but may rather directly contribute to local inflammation and thrombus formation." (PMID 39412036, 2024). "In addition, our study also found that, unlike the patients with acute noncardiogenic precirculatory infarction, the elevation of initial serum CRP also has a certain evaluation value for the prognosis of patients with acute noncardiogenic precirculatory infarction." (PMID 36535282, 2022). "In addition, VBI was regarded as acute stroke in our study, and this disease may only result in transient ischemic symptoms without an identifiable infarction lesion on brain MRI and may also have contributed only to a minimal increase in CRP levels." (PMID 34135849, 2021). "In addition, age, BMI, infarct volume, the NIHSS score, and blood levels of FBG and Hs-CRP remained significant outcome predictors, unlike all others assessed." (PMID 29588341, 2018).